Y_RNA (Y RNA )
Gene: Miscellaneous RNA gene on chromosome 1 (202,070,841 to 202,070,943, forward strand). Ensembl gene ENSG00000212512.
Homologues: Orthologues: chimpanzee Y_RNA (100% identical). Paralogues in human: Y_RNA (82% identical), Y_RNA (81% identical), Y_RNA (78% identical), Y_RNA (77% identical), Y_RNA (76% identical), Y_RNA (75% identical), RNY3 (74% identical), RNY3P12 (74% identical), Y_RNA (74% identical), RNY3P1 (73% identical), RNY3P16 (73% identical), Y_RNA (73% identical), and 88 more.